LPL (lipoprotein lipase)
Diseases named in the same sentence as LPL in open-access papers (continued):
Sharing a sentence is not in itself a finding about the gene and the disease.
cardiovascular disease (continued). "Angptl4 plays a role in the regulation of TG homeostasis and lipid metabolism by suppressing lipoprotein lipase (LPL) activity, and common non-coding variants in LPL gene loci and TGs levels are associated with cardiovascular diseases." (PMID 40296165, 2025). "In clinical practice, plasma LPL concentration is a useful biomarker for a few cardiovascular diseases." (PMID 37686357, 2023). "LPL expression in macrophages, adipocytes and cardiomyocytes has been proposed to affect cardiovascular disease, with a pro-atherogenic effect when expressed in macrophages, anti-atherogenic in adipocytes, and myopathy-promoting in cardiomyocytes." (PMID 37906604, 2023). "ApoC3 plays a central role in the hydrolysis process of triglyceride (TG)-rich lipoproteins mediated by lipoprotein lipase (LPL), which levels are positively associated with the incidence of cardiovascular disease (CVD)." (PMID 35187136, 2022). "ANGPTL4 has surfaced as a principal regulator of plasma lipid metabolism by functioning as a potent inhibitor of lipoprotein lipase in cardiovascular disease." (PMID 35285130, 2022). "We also demonstrated confirmatory evidence for the causal role of four further proteins (FGF5, IL6R, LPL, LTA) in cardiovascular disease risk." (PMID 32628676, 2020). "In general, women are more likely to have greater gynoid fat distribution, and having this distribution is thought to oppose cardiovascular diseases through more efficient fat storage/lipoprotein lipase functionality." (PMID 23566334, 2013). "For example, the ADIPOQ, AMY1A, CFB, HP and HBB are associated with the metabolic diseases, while the FBP4, HP, LPL and MYL2 are related to the cardiovascular diseases." (PMID 24204599, 2013). "Triglycerides are not directly atherogenic, but represent an important biomarker of cardiovascular disease risk because of their association with atherogenic remnant particles and apolipoprotein C-III, a lipoprotein lipase (LPL) inhibitor." (PMID 23122449, 2012). "Collagens (COL1A, COL3A), lipoprotein lipase (LPL), and fatty-acid binding proteins (FABPs) involved in cardiovascular diseases and lipid metabolisms were upregulated by a high-fat diet and downregulated by resveratrol." (PMID 22822401, 2012). "According to this study, LPL could play a key role in messing up the lipid metabolism of patients with cardiovascular disease." (PMID 41373652, 2025). "Based on our findings, we believe that LPL may have a role in the inflammatory dyslipidemia and cardiovascular disease found in IBD patients." (PMID 36982268, 2023). "The positive effects observed on LPL activity and NO production suggest that these extracts could help manage both lipid metabolism and endothelial function, two critical factors in the prevention and treatment of cardiovascular diseases." (PMID 40223248, 2025). "Hence, further investigations into the molecular genetics and functions of LPL in the context of metabolic and cardiovascular diseases in T2D patients will be necessary to design new therapeutic approaches for enhancing metabolic and cardiac quality of life in this continuously expanding population." (PMID 41373652, 2025). "Thus, the ‘biological distance’ between ANGPTL3 and cardiovascular disease may be greater than for LPL and ANGPTL4, suggesting that statistical power may also be lower, even if the relative efficacy of these drug targets might be similar in clinical practice." (PMID 39407214, 2024). "As a regulator of lipoprotein lipase, ANGPTL4 modulation impacts lipid homeostasis, thus rendering it a promising therapeutic target for cardiovascular disorders." (PMID 40006981, 2025). "Optimization of LPL expression and activity in WAT will reduce plasma TG levels, which can ultimately reduce the incidence of cardiovascular disease in conjunction with successful LDL-C reduction." (PMID 38973609, 2024).
cardiovascular disease (continued). "For example, there is strong genetic evidence implicating both lipoprotein lipase (LPL) and angiopoietin-like protein 4 (ANGPTL4) as therapeutic targets for lipid-lowering and cardiovascular disease reduction." (PMID 39407214, 2024). "Whether V227A-mediated plasma triglyceride reduction imparts any long-term cardiometabolic protection is not yet known, but there is clinical interest in promoting LPL activity for the prevention of cardiovascular disease." (PMID 40245984, 2025).
metabolic disorders (53 papers, 2009 to 2026). "Since FCS is a genetic deficiency in functional lipoprotein lipase, conventional triglyceride-lowering therapies are ineffective in this metabolic disorder." (PMID 42319369, 2026). "Specifically, the Lpl gene which encodes lipoprotein lipase, breaking down metabolic disorder-leading triglycerides, was exclusively up-regulated in endothelial and macrophage clusters in males." (PMID 41082647, 2025). "The rationale behind the study is based on previous reports that described the importance of investigating non-coding variants in the LPL gene locus for their possible association with metabolic disorders." (PMID 40806414, 2025). "The high frequency of the minor allele of the LPL gene (36.0%) indicates a predisposition to metabolic disorders." (PMID 41234028, 2025). "This study adds to the ongoing research that attempts to identify ethnicity-specific variants in the apolipoprotein gene loci and associated LPL genes to elucidate the molecular mechanisms of metabolic disorders." (PMID 38003484, 2023). "Lipoprotein lipase (LPL) deficiency is a lipoprotein metabolism disorder inherited in an autosomal recessive manner caused by dysfunction of the LPL gene." (PMID 34544385, 2021). "Glybera is based on an adeno-associated viral (AAV) vector and gained approval for the treatment of a genetically inherited metabolic disorder related to the gene encoding the lipoprotein lipase (LPL)." (PMID 29124055, 2017). "Utilization and processing of glucose as well as glucose uptake capacity of muscle and adipose tissue are decreased, hepatic glucose production is increased, and activity of lipoprotein lipase decreased, causing glucolipid metabolic disorders." (PMID 26246836, 2015). "In contrast, the high frequency of the minor allele of the LPL gene (36.0%) associated with lipid metabolism may indicate a higher predisposition to metabolic disorders in the Kazakh population." (PMID 41234028, 2025). "A high frequency of the minor allele of the LPL gene indicates a predisposition to metabolic disorders, which may influence the risk of vascular complications." (PMID 41234028, 2025). "Thus, we have provided more evidence that LPL hypermethylation can predispose to metabolic diseases like T2D." (PMID 36535927, 2022). "Prolonged sitting behavior may cause metabolic disorders such as the uptake of free fatty acids into muscle cells and the suppression of lipoprotein lipase activity required for HDL production." (PMID 34200000, 2021). "The LPL SNPs rs301 (T<C), rs328 (C<G) and rs13702 (T<C) have been associated with various metabolic disorders, but the association with CLL evolution is unknown." (PMID 25811490, 2015). "The LPL SNPs rs301 (T<C), rs328 (C<G) and rs13702 (T<C) have been associated with various metabolic disorders, such as insulin resistance and atherosclerosis, but the association with CLL disease evolution is unknown." (PMID 25811490, 2015). "The association between testosterone levels and chronic diseases, as well as metabolic disorders, is bidirectional: reduced TT levels result in heightened lipoprotein lipase expression and VAT buildup." (PMID 40061456, 2025). "Increased serum levels or activities of LPL and HL can lead to increased lipid clearance, resulting in reduced TG and metabolic disorder mitigation." (PMID 38790610, 2024). "Understanding the mechanisms that determine the tissue-specific activity of LPL during the feed/fast cycle carries significant implications for human health and metabolic diseases." (PMID 38521668, 2024). "Lipoprotein lipase (LPL) is responsible for the hydrolysis of lipoproteins; hence defective LPL is associated with metabolic disorders." (PMID 35456470, 2022). "Conversely, in brown adipose tissue LPL upregulation exerts positive effects on metabolic disease by burning excess calories through activation of mitochondrial thermogenesis." (PMID 35734882, 2022).
metabolic disorders (continued). "Collectively, these results support future studies to identify potentially cohesive mechanisms underlying lipoprotein lipase- and CD36-mediated nerve injury in metabolic disease, and their potential as therapeutic targets for PN treatment." (PMID 31822493, 2020). "The evidence on ANGPTL4-mediated blood lipid regulation comes from animal studies, while data on the relationship between ANGPTL4 and LPL expression in AT and metabolic diseases in humans are very limited." (PMID 33003532, 2020). "Prolonged periods of sedentary behavior has been linked to suppression of lipoprotein lipase (LPL) activity in skeletal muscle due to loss of local muscle contraction, which may be the possible pathway underlying the relationship of sedentary time and vascular and metabolic diseases." (PMID 25526746, 2014). "The ApoE gene may be crucial for storage of fat in the thigh since it limits LPL-mediated hydrolysis of triglycerides and LPL activity is positively correlated to thigh exercise which can raise metabolic rate and help with metabolic disease." (PMID 39598239, 2024). "We conclude that APOE on VLDL modulates LPL activity and could be a relevant factor in the pathogenesis of metabolic disease." (PMID 34863862, 2022). "LPL is a therapeutic target for multiple types of metabolic diseases." (PMID 34632719, 2021). "Moreover, mutations in Lipoprotein Lipase (LPL), which is crucial for receptor-mediated lipoprotein uptake, drastically affect lipoprotein metabolism disorders (NCBI 4023)." (PMID 22536488, 2012). "Since both LPL and GHRL are involved in energy metabolism, these findings suggest the potential for sex-based differences in the pathophysiology of metabolic diseases in humans." (PMID 41238731, 2025). "Augmented visceral fat lipolysis through adipose tissue lipoprotein lipase stimulates the excessive generation of FFA, resulting in IR and metabolic diseases, such as T2DM." (PMID 36127704, 2022). "Measuring the activity or expression levels of signaling molecules (FAS, ATGL, LPL, PPARs, MMPs, α-SMA, and certain indicative proteins) and transcription factors can provide insights into their mechanisms of action in fibrosis, metabolic disorders, and chronic diseases." (PMID 37895842, 2023). "However, the methylation levels in the genes involved in lipid metabolism, such as lipoprotein lipase (LPL) essential in storing or consuming triglycerides, are altered in obese patients with the metabolic disease, indicating a difference from healthy people." (PMID 33142938, 2020). "PPARs participate in mediating metabolic disorders via downstream genes which are important for adipocyte maturation, lipid accumulation, and insulin-sensitive glucose transport, including PGC1-α, PGC1-β, aP2, LPL, ACC, ACO, CD36, UCP-2 and Glut4." (PMID 24312343, 2013).
infection (29 papers, 2011 to 2025). The state of being infected such as from the introduction of a foreign agent such as serum, vaccine, antigenic substance or organism. "Infection of skeletal muscle with an adeno-associated virus encoding a gain of function human LPL (hLPL) variant also rescues the neonatal lethality but is transient, as these viruses do not integrate into the genome and hLPL expression decreases over time." (PMID 29304082, 2018). "We conducted longitudinal assays for endothelial lumen-associated LPL and triglyceride levels to determine if infection with RCAS-hLPL increased post-heparin plasma LPL activity and reduced serum triglyceride levels." (PMID 29304082, 2018). "Infection also led to the expression of a variety of genes encoding secreted lipases such as the Lipoprotein lipase precursor (lpl) (1.7 fold) that preferentially hydrolyzes triglycerides." (PMID 22928052, 2012). "Before infection, the expression levels of LPL and PPAR-α in fish in 0.5–4‰ treatments were significantly higher than those in fish in control, 0.5 and 8‰ treatments." (PMID 34305652, 2021). "Despite the reduction in post-heparin LPL activity, triglyceride levels remained low one month post-infection, demonstrating that sufficient hLPL was produced systemically to reduce triglycerides." (PMID 29304082, 2018). "Serum triglyceride levels and post-heparin plasma LPL activity assays were conducted at 4 week intervals beginning 20 weeks prior to infection." (PMID 29304082, 2018). "In the first step, an MSCV vector comprising a recombinant LPL coding sequence was constructed, and it exhibited high infection rates." (PMID 28969646, 2017). "The infection of cells with the two virus strains was inhibited by more than 90% in the presence of LPL." (PMID 22039521, 2011). "Despite these potential differences, the infection of cells with these two HCVcc strains was equally inhibited by LPL." (PMID 22039521, 2011). "We show that LPL inhibits cell infection with the viruses produced in cultured Huh7.5 cells or in chimeric uPA-SCID mice into which primary human hepatocytes are grafted." (PMID 22039521, 2011). "Together, these two functions of LPL facilitate the retention of the virus at the cell surface, significantly decreasing infection levels." (PMID 22039521, 2011). "This intriguing observation led us to investigate further the influence of LPL on cell infection by HCV." (PMID 22039521, 2011). "In our study, LPL inhibited infection with “low-density” and “high-density” viral populations isolated from cell supernatants or from “humanized” mouse sera." (PMID 22039521, 2011). "Cell infection with these two virus strains produced in chimeric mice was strongly inhibited in the presence of LPL, like infection with viruses produced in Huh7.5 cells." (PMID 22039521, 2011). "Viruses produced in vitro or in vivo were separated on iodixanol gradients into low and higher density populations, and the infection of Huh 7.5 cells by both virus populations was inhibited by LPL." (PMID 22039521, 2011). "To determine whether triglyceride uptake is necessary for fluoxetine mediated protection, we administered Pluronic F-127 to mice during infection to inhibit LPL activity and triglyceride uptake and monitored disease progression." (PMID 39951524, 2025). "One plausible hypothesis is that laparoscopic lavage amplifies the peritoneal recruitment of macrophages through raised levels of LPL, thereby modulating the local immune response against infection." (PMID 40102905, 2025). "Simultaneously, the infection and inflammation may inhibit the activity of lipoprotein lipase, leading to reduced clearance of triglycerides." (PMID 37720148, 2023). "The increased mRNA levels of apolipoprotien E (ApoE) and lipoprotein lipase (LPL) observed in Cpn-infected astrocytes relative to uninfected cells at 6 hpi may therefore be necessary to allow Cpn to initiate infection within the astrocyte host." (PMID 30786875, 2019).
infection (continued). "At one month following infection heparin-releasable LPL activity decreased significantly, suggesting either a reduction of hLPL production in vivo or the mice developed antibodies against the human LPL protein." (PMID 29304082, 2018). "To test this hypothesis, we examined tissue LPL activity in mice with either antibody injection or adenovirus-lipasin infection." (PMID 26687026, 2015). "Thus, the addition of LPL to Huh7.5 cells as an exogenous ligand inhibited cell infection with various HCVcc strains." (PMID 22039521, 2011). "Our data show that exogenous LPL increases viral attachment to the cell surface, but strongly inhibits infection of the cell by HCV, by two mechanisms: lipolytic activity and “molecular bridging”, together leading to the retention of virus particles at the cell surface." (PMID 22039521, 2011). "We therefore hypothesized that LPL could either block the virus at the cell surface, or internalize it by the non productive pathway, leading to abortive infection." (PMID 22039521, 2011). "We investigated whether LPL inhibited cell infection with the same virus strains produced in primary human hepatocytes transplanted into chimeric mice." (PMID 22039521, 2011). "We therefore investigated whether LPL could also inhibit cell infection with the same two virus strains produced under more natural conditions, in primary human hepatocytes transplanted into chimeric uPA-SCID mice with normal lipoprotein metabolism." (PMID 22039521, 2011). "However, the lipase inhibitor tetrahydrolipstatin restored only a minor part of HCV infectivity, suggesting an important role of the LPL bridging function in the inhibition of infection." (PMID 22039521, 2011). "Additionally, serum lipid levels have been reported to increase following infection or inflammatory response, perhaps due to increased lipolysis and decreased lipoprotein lipase activity, which alters the uptake and utilization of fatty acids during an inflammatory response." (PMID 38891571, 2024). "Infection severity is inversely proportional to the VLDL elimination due to reduced apolipoprotein E and lipoprotein lipase." (PMID 38449886, 2024). "Accordingly, DRE sites in lipid-related genes such as Lipoprotein lipase (Lpl) and CDP Diacylglycerol Synthase 2 (Cds2) were upregulated after infection." (PMID 37081881, 2023). "The DEGs involved in amino acid biosynthesis and energy metabolic processes were GOT1, CBSL, SOCS1, LPL and STC2, and their expressions were largely down‐regulated in response to H37Rv infection." (PMID 34632719, 2021). "To summarize the effects of miR-122 inhibition on lipid metabolism and insulin signaling, we showed that miR-122 inhibition leads to an increase in LPL, GLUT4 and FABPs at 4 days post-infection of miR-122 inhibitor." (PMID 30024933, 2018). "After infection with the MSCV-hLPL virus, the LPL activity of each cell line increased dramatically at the cell surface, compared with the respective control groups transfected with the empty control virus." (PMID 28969646, 2017). "Each cell line used in this study can not only produce lipoprotein lipase after infection with the MSCV-hLPL virus, but can also efficiently secrete LPL to the cell surface, which is a necessary precondition for proper lipoprotein lipase function." (PMID 28969646, 2017). "Our previous experiments suggested that LPL inhibited cell infection with HCVcc (JFH-1 strain), with a large decrease in virus production observed 24 h, 48 h and 72 h post-infection." (PMID 22039521, 2011). "Activated macrophages can inhibit lipoprotein lipase production to increase triglyceride levels by releasing TNF-α and IL-1 which may also be another factor that can promote the occurrence of infection." (PMID 36117592, 2022). "The frequency of α4β7+ cells was generally lower on LNMC than on LPL for all studied subsets regardless of the infection status." (PMID 31356607, 2019).